AFP (alpha fetoprotein)
Diseases named in the same sentence as AFP in open-access papers (continued):
Sharing a sentence is not in itself a finding about the gene and the disease.
liver cancer (continued). "Simultaneously, AFP can attenuate its cytotoxicity toward liver cancer cells by regulating signaling pathways in NK cells." (PMID 38660138, 2024). "The combination of exosomal circ‐CDYL and plasma protein AFP can effectively diagnose liver cancer (the value of AUC is 0.896), providing a promising diagnostic strategy for liver cancer." (PMID 39584047, 2024). "Serum AFP was the first known tumor marker, identified in the blood of patients with liver cancer and certain other cancers." (PMID 39583507, 2024). "There is a scarcity of biomarkers exhibiting high sensitivity and specificity, such as PSA for prostate cancer and AFP for liver cancer." (PMID 38706913, 2024). "Alpha-fetoprotein (AFP) is the predominant serum biomarker for liver cancer screening in LIHC patients." (PMID 38955924, 2024). "Using two distinct short-interfering RNAs (siAFP 1#,2#), we knocked down AFP expression in the AFP-producing gastric cancer cell line, Fu97, and liver cancer cell line, Hep3B." (PMID 39135041, 2024). "Fast and efficient detection of alpha-fetoprotein (AFP) plays a crucial role in early liver cancer diagnosis." (PMID 38735927, 2024). "As a serum indicator of primary liver cancer, AFP can be used to diagnose and track the effectiveness of HCC treatments." (PMID 38339301, 2024). "Serum alpha-fetoprotein (AFP) and liver ultrasound are the two most commonly used methods for liver cancer screening." (PMID 39650722, 2024). "Serum alpha-fetoprotein (AFP) levels play an important role in distinguishing HH from malignant liver tumors such as hepatoblastoma." (PMID 38792380, 2024). "The patients included in the study had a precise diagnosis of liver cancer, characterized by an elevated alpha-fetoprotein (AFP) level exceeding 400 μg/L and positive results from one or more dynamic imaging tests." (PMID 39367397, 2024). "The goal of this research work is to develop an efficient, cost-effective, and easy-manufactured electrochemical biosensor utilizing laser-induced graphene for the detection of liver cancer diagnosis (AFP) and E2." (PMID 39065385, 2024). "Some clinical characteristics, such as alpha fetoprotein (AFP), microvascular invasion, Barcelona Clinic Liver Cancer (BCLC) stage and treatment methods, are used to predict HCC survival." (PMID 39163514, 2024). "Two representative groups of human liver cancer cell lines have been proposed to mimic ‘early-stage’, well-differentiated (AFP+) and ‘late-stage’, poorly differentiated (AFP−) HCC, respectively." (PMID 39112713, 2024). "Currently, the most commonly employed prognostic assessment tools for liver cancer include alpha-fetoprotein (AFP), liver function tests, and imaging modalities." (PMID 39742265, 2024). "α-Fetoprotein (AFP) is an oncogenic glycoprotein that is overexpressed in most patients with liver cancer." (PMID 39990947, 2024). "AFP is a sensitive indicator of liver cancer, and as its serum marker, the abnormal increase in AFP value is helpful for the early detection of liver cancer." (PMID 39791624, 2024). "LCSCs-derived AFP can facilitate immune evasion by regulating the behavior of crucial immune cells in liver cancer cells." (PMID 38660138, 2024). "Alpha-fetoprotein (AFP) is extensively employed in clinical practice for the diagnosis of liver cancer and assessment of treatment effectiveness [50, -52]." (PMID 38494878, 2024). "In particular, AFP measurement is critical for the early warning and prognosis evaluation of liver cancer, hepatitis, and other liver diseases." (PMID 39771616, 2024). "We performed glycosylation mass spectrometry analysis on AFP extracted from normal HEK 293F cells and liver cancer cells Bel7042 (293-AFP and 7402-AFP)." (PMID 38678117, 2024). "To overcome this limitation, we fabricated cationic lipid nanoparticles (cLNPs) to deliver AFP-targeted siRNA (siAFP) to AFP-producing liver cancer cells." (PMID 39990947, 2024).
liver cancer (continued). "Secondly, AFP is also involved in the interaction between liver cancer cells and the immune microenvironment." (PMID 38660138, 2024). "Although elevated serum AFP levels are common during the proliferative phase of HHs, a rising trend in AFP levels during follow-up warrants the suspicion of malignant liver tumors." (PMID 38792380, 2024). "Their findings revealed that AFP can facilitate the polarization of macrophages toward the M2 phenotype and undermine the phagocytic ability of M1 macrophages toward liver cancer cells." (PMID 38660138, 2024). "On the other hand, serum IL-41 expression was positively correlated with ALT and AST levels in AFP-positive liver cancer patients." (PMID 38835390, 2024). "Abnormal elevation of AFP is common in patients with chronic or active hepatitis, liver cirrhosis, liver cancer, genital tumors, and pregnancy, and approximately 70% of patients with liver cancer have elevated serum AFP levels." (PMID 36911723, 2023). "To evaluate differential expression of key CmPn players and their potential role as prognostic biomarkers, we also profiled AFP, an established liver cancer biomarker, to compare with our CmPn profiling analysis." (PMID 36980321, 2023). "For instance, alpha-fetoprotein (AFP) in human serum is generally regarded as an important biomarker of HCC for targeting liver cancer analysis." (PMID 37284243, 2023). "Significantly, HBx stimulates alpha-fetoprotein (AFP) expression, leading to hepatocyte reprogramming and impacting liver cancer development." (PMID 38188582, 2023). "Aside from its role in liver cancer diagnostics, AFP is considered a target for liver cancer immunotherapy." (PMID 37377916, 2023). "Markers included CA 125 for ovarian cancer, Cyfra21-1 for lung cancer, CA15-3 for breast cancer, CA19-9 for pancreatic cancer, carcinoembryonic antigen (CEA) for colorectal, pancreatic, breast, and lung cancer, and alpha-fetoprotein (AFP) for liver cancer." (PMID 37760525, 2023). "Alpha-fetoprotein (AFP) is the current gold standard biomarker for diagnosing liver cancer, but it has variable sensitivity and specificity and is often used as a complementary biomarker." (PMID 36980321, 2023). "Liver cancer patients have elevated AFP in serum up to 400 ng/mL compared to healthy individuals below 25 ng/mL." (PMID 37366982, 2023). "At present, the most commonly used biomarker for the early diagnosis of liver cancer is alpha-fetoprotein (AFP), but AFP is sensitive to interference from other factors and cannot really be used as the basis for determining liver cancer." (PMID 36980210, 2023). "AFP, derived from fetal hepatocytes and yolk sacs, has been widely used as a useful cancer biomarker in the diagnosis of liver cancers." (PMID 37575092, 2023). "At present, the primary method for early screening of liver cancer is measuring the serum AFP levels." (PMID 37546394, 2023). "The rapid and accurate detection of alpha-fetoprotein (AFP) levels is of great significance for the diagnosis and later treatment evaluation of liver cancer." (PMID 37175021, 2023). "Products of Cyp, such as 14,15-DHET have been found to correlate with liver cancer diagnosis marker alpha fetoprotein (AFP) in HBV-related HCC patient samples and NASH/fibrosis." (PMID 36818443, 2023). "Before 1970, the two-way agar diffusion method was mainly used, and the specificity of AFP in the diagnosis of primary liver cancer was satisfactory." (PMID 37781207, 2023). "AFP is a glycoprotein (approximately 70 kDa) produced by the fetal liver and yolk sac and plays an important role in the occurrence and development of liver cancer." (PMID 37283795, 2023). "Although the alpha-fetoprotein level was within the normal range, differentiating it from primary liver cancer remained difficult, necessitating further liver-enhanced CT and MRI for diagnosis." (PMID 38115256, 2023). "In 1964, Tatarinov reported the first case in which the serum AFP levels were elevated in the sera of a liver cancer patient." (PMID 36672339, 2023).
liver cancer (continued). "This sensing system was further validated by detecting AFP values from clinical serum samples, which were obtained from pregnant women, liver and lung cancer patients and those undergoing liver cancer screening." (PMID 37887110, 2023). "For example, in liver cancer, the most widely used biomarker, AFP, suffers from poor specificity; thus, more research is needed to find alternative biomarkers." (PMID 36980210, 2023). "In adults, AFP can be elevated in about 80% of liver cancer patients; the level of serum AFP is positively correlated with the size of the liver cancer, which is a sign of high tumor invasiveness." (PMID 37670232, 2023). "In sum, our clinical data support the future use of CmPn members’ expression data, confirmed with AFP, as potential prognostic biomarkers for distinguishing between primary subtypes of liver cancer and evaluating tumor recurrence in patients." (PMID 36980321, 2023). "It is noteworthy that the performance of our 8-gene signature in distinguishing HCC patients from normal samples and early-stage liver cancer is superior to AFP.." (PMID 38114725, 2023). "Although the sensitivity of miRNA-122 in the diagnosis of liver cancer is better than that of AFP, it still has its shortcomings." (PMID 37546394, 2023). "We also explored that the mRNA expression levels of AP4M1 in liver cancer patients at AFP > 400 were significantly higher than in the AFP ≤ 400ng/ml group." (PMID 37821948, 2023). "Only two studies were used to assess the relationship between CTC-WBCs and tumor size, AFP level, and liver cirrhosis in liver cancer." (PMID 38087278, 2023). "Given the importance of tumor microenvironments for both tumorigenesis and immunogenicity in hepatic cancers, one of our main tasks was also to assess differential expression of CmPn network genes, along with AFP, among immune subtypes for both HCCs and CCAs." (PMID 36980321, 2023). "Prior to sacrifice, we performed magnetic resonance imaging (MRI) and serum α-fetoprotein (AFP, a marker for liver cancer) detection, both of which inferred accelerated liver tumorigenesis in Mettl3LKI mice." (PMID 37586322, 2023). "Biochemical parameters of liver function (AST, ALT, GGT) and liver cancer biomarkers (AFP, CA19.9 e CEA) were evaluated by standard assays." (PMID 38110968, 2023). "Zheng’s study found that LAMP2 expression was significantly reduced in liver cancer and was correlated with metastasis, serum alpha-fetoprotein levels, vascular invasion, recurrence, and poor prognosis of liver cancer." (PMID 37986192, 2023). "An experimental study demonstrated that AFP has a regulatory role in angiogenesis and cell invasion during liver cancer development." (PMID 36672339, 2023). "Among them, the arterial embolization prognosis (HAP) score of liver cancer combined with tumor size, alpha-fetoprotein (AFP), bilirubin, and albumin values was used for prognostic evaluation." (PMID 37208604, 2023). "If a tumor mass is suspected of primary liver cancer showing elevated serum levels of both alpha-fetoprotein (AFP) and carbohydrate antigen 19.9 (CA 19-9), the diagnosis of cHCC-CC is very likely." (PMID 36765731, 2023). "The screening for liver cancer becomes easier with the widespread and convenient application of liver ultrasonography and the serum marker alpha-fetoprotein (AFP)." (PMID 37639192, 2023). "Further, as the level of AFP is also related to the stage of the disease, identification of AFP is of great interest for the early diagnosis and clinical treatment of liver cancer." (PMID 37366982, 2023). "Research has demonstrated that higher AFP levels are correlated with larger tumour size, vascular invasion, and advanced-stage disease in patients with unresectable liver cancer." (PMID 37780370, 2023). "Nomograms combining ALI and AFP can give clinicians with predictive information on liver cancer survival, hence providing some reference value for immunotherapy in advanced liver cancer patients." (PMID 36998452, 2023).
liver cancer (continued). "In the same cohort, the discriminative ability of liver cancer for AFP was 0.502 (95% CI: 0.418-0.586), indicating that RRM1 and RRM2 had great potential to be diagnostic biomarkers for liver cancer." (PMID 36713030, 2023). "A series of studies from a Japanese liver cancer research team showed that 19% of patients with intrahepatic CCA had a serum AFP level greater than 20 ng/mL, 10.3% had greater than 200 ng/mL, and only 6.3% had greater than 1000 ng/mL." (PMID 36673043, 2023). "Recent research has investigated PIVKA-II and AFP as potential predictive markers for unresectable liver cancer." (PMID 37780370, 2023). "Alpha-fetoprotein (AFP) is the only clinical applied biomarker for diagnosis of early liver cancer which lacks accuracy as 32%~59% of liver cancer patients display normal AFP." (PMID 36918840, 2023). "Three different Raman tags were attached to Au nanoparticles which were then appropriately modified for the coupling of antibodies against three liver cancer markers, namely, AFP, CEA, and ferritin." (PMID 37241360, 2023). "We compared age, sex, etiology, Child–Pugh score, platelet count, albumin, total bilirubin, prothrombin time, ALBI score, tumor size, number of nodules, alpha-fetoprotein, des-γ-carboxy prothrombin, Barcelona Clinic Liver Cancer, and previous TACE." (PMID 36765804, 2023). "For example, the molecular detection of alpha fetoprotein (AFP) enables early detection of liver cancer and improvement of prognosis, while the introduction of prostate specific antigen (PSA) screening significantly reduces the mortality of prostate cancer." (PMID 37570630, 2023). "The quantification of alpha-fetoprotein (AFP) as a potential liver cancer biomarker which is generally found in ultratrace level is of significance in biomedical diagnostics." (PMID 37284243, 2023). "The surface was used for the construction of an immunosensor for the detection of alpha-fetoprotein, which is a liver cancer biomarker." (PMID 36979545, 2023). "To date, the AFP level is recommended for routine screening, diagnosis, and prognostic stratification of liver cancer." (PMID 36915049, 2023). "Up to now, AFP is the only widely used screening biomarker for the clinical practice of the liver cancer by the National Health Commission of the People's Republic of China." (PMID 36587394, 2023). "AFP is a tumor biomarker of liver cancer, serum ALT and AST levels are characteristic indexes reflecting liver function, and tumor necrosis factor TNF-α is an important inflammatory factor." (PMID 36110518, 2022). "Additional analysis with Wilcoxon's test confirmed that AFP-positive liver cancer cells (average rank: 38.50) were significantly more sensitive to gemcitabine than AFP-negative cells (average rank: 25.79) (W = 490.000, Z = −2.567, P=0.010)." (PMID 35127582, 2022). "Alpha fetoprotein is a crucial molecule that promotes proliferation or drug resistance in liver cancer cells." (PMID 36181321, 2022). "The AFP level in healthy human serum is less than 25 ng ml-1, but it rises dramatically in individuals with liver cancer." (PMID 36389169, 2022). "AFP is a standard marker for the early diagnosis of primary liver cancer in clinics, and AFP expression level negatively correlates with patient survival rate." (PMID 36532852, 2022). "The results indicate that AFP has the highest sensitivity and can be used for early screening of ocular metastases from liver cancer." (PMID 36199582, 2022). "According to the instruction of Guidelines for Diagnosis and Treatment of Primary Liver Cancer (2022), AFP is a common biomarker for the diagnosis of liver cancer and curative effect." (PMID 36293016, 2022). "In CCl4-induced liver cancer, selenium was observed to decrease the elevation of alpha-fetoprotein (AFP) and TNF-α compared with control mice." (PMID 35624786, 2022). "The current results showed that gemcitabine had a greater inhibitory effect against AFP-positive compared with AFP-negative liver cancer cells in vitro HDS." (PMID 35127582, 2022).
liver cancer (continued). "Because of the advantages of convenient and inexpensive serum markers for diagnosing liver cancer, It is hoped that new serum markers for liver cancer can be found to compensate for the shortage of AFP." (PMID 36341438, 2022). "This indicates that including AFP in health screening is cost-effective, especially in areas with low HCC prevalence, as close surveillance for liver cancer is mandated only for those with elevated AFP levels." (PMID 35632726, 2022). "The aberrant expression of AFP in liver cancer is a crucial determinant in clinical diagnosis and liver cancer prediction." (PMID 36425563, 2022). "The traditional diagnosis of liver cancer relies on the detection of serum alpha-fetoprotein (AFP) and imaging methods such as ultrasound and magnetic resonance." (PMID 36145508, 2022). "Seral-CCT3 was increased in liver cancer patients compared to normal patients and correlated with other serum markers like alpha-fetoprotein (AFP)." (PMID 35602608, 2022). "Currently, alpha-fetoprotein (AFP) for liver cancer, prostate-specific antigen (PSA) for prostate cancer, and carcinoembryonic antigen (CEA) for colon cancer are all glycosylated proteins that have been used as biomarkers in clinical application." (PMID 35782861, 2022). "The reported effectiveness and safety of the combination of L-OHP and EPI warrant further studies of their effects in the treatment of AFP-positive liver cancer." (PMID 35127582, 2022). "AFP is the most common serum marker for liver cancer detection, and an AFP test every 6 months carries a high clinical value for liver cancer screening and prognostic assessment." (PMID 35401747, 2022). "BCLC stage and baseline AFP level were indispensable clinical indicators to assess prognosis of liver cancer." (PMID 35311090, 2022). "AFP is synthesized in large amounts in fetal hepatocytes and undifferentiated liver cancer cells, and is therefore a specific marker of liver cancer." (PMID 35251971, 2022). "Alpha-fetoprotein (AFP) is currently the most common tumor marker in the diagnosis of liver cancer, but clinical experience has revealed its mediocre sensitivity and specificity." (PMID 35401747, 2022). "AFP is a well-known basic marker that increases in liver cancer, and CEA is also important in case of metastases to this organ." (PMID 35122196, 2022). "As the most commonly used protein biomarker for liver cancer diagnosis, alpha-fetoprotein (AFP) has attracted much attention in recent years." (PMID 36290918, 2022). "Alpha fetoprotein (AFP) is the main biomarker of liver cancer, as expression is undetectable in healthy adults, yet high levels are detected in ~80% of HCC cases." (PMID 35857843, 2022). "Alpha fetoprotein (AFP) is an important cancer biomarker of liver cancer, currently detecting AFP relays via instrumental means." (PMID 36421153, 2022). "The levels of liver cancer biomarker AFP, liver injury indicators ALT, AST and pro-inflammatory factor TNF-α in serum of rats treated with LFE were significantly lower than those in model group and close to blank group." (PMID 36110518, 2022). "Alpha fetoprotein (AFP) is a type of glycoprotein that is closely related to the occurrence of liver cancer and a variety of tumors, and can be used as a serum marker of liver cancer in the clinical setting." (PMID 35630141, 2022). "The AFP levels were significantly higher in the experimental versus the control group, indicating the success of liver cancer modeling." (PMID 35251971, 2022). "The area under the ROC curve for the diagnosis of liver cancer by AFP was 0.747 (0.581∼0.931), and the best cutoff value was 187.65." (PMID 35237392, 2022). "The AFP data from pathology reports revealed that HBL patients with an active β-catenin-TCF4-CEGRs/ALCDs pathway had high levels of AFP protein in their serum samples, consistent with other reports that increased AFP is a signature of liver cancer." (PMID 36551548, 2022).